IGLV3-1 (immunoglobulin lambda variable 3-1)
Description:
V region of the variable domain of immunoglobulin light chains that participates in the antigen recognition. Immunoglobulins, also known as antibodies, are membrane-bound or secreted glycoproteins produced by B lymphocytes. In the recognition phase of humoral immunity, the membrane-bound immunoglobulins serve as receptors which, upon binding of a specific antigen, trigger the clonal expansion and differentiation of B lymphocytes into immunoglobulins-secreting plasma cells. Secreted immunoglobulins mediate the effector phase of humoral immunity, which results in the elimination of bound antigens. The antigen binding site is formed by the variable domain of one heavy chain, together with that of its associated light chain. Thus, each immunoglobulin has two antigen binding sites with remarkable affinity for a particular antigen. The variable domains are assembled by a process called V-(D)-J rearrangement and can then be subjected to somatic hypermutations which, after exposure to antigen and selection, allow affinity maturation for a particular antigen.
Tractability: Antibody: UniProt places it where antibodies can reach, with medium confidence; UniProt predicts a signal peptide or a membrane-spanning region; its Gene Ontology location is reachable by antibodies, with medium confidence.
Gene: Immunoglobulin variable (V) gene on chromosome 22 (22,880,706 to 22,881,396, forward strand). Ensembl gene ENSG00000211673.
Subcellular location: Secreted; Cell membrane
Pathways (Reactome):
Immune System: Antigen activates B Cell Receptor (BCR) leading to generation of second messengers; CD22 mediated BCR regulation; Classical antibody-mediated complement activation; FCERI mediated Ca+2 mobilization; FCERI mediated MAPK activation; FCERI mediated NF-kB activation; FCGR activation; Fc epsilon receptor (FCERI) signaling; Immunoregulatory interactions between a Lymphoid and a non-Lymphoid cell; Initial triggering of complement; Regulation of Complement cascade; Regulation of actin dynamics for phagocytic cup formation; Role of LAT2/NTAL/LAB on calcium mobilization; Role of phospholipids in phagocytosis
Disease: FCGR3A-mediated IL10 synthesis; FCGR3A-mediated phagocytosis; Potential therapeutics for SARS
Hemostasis: Cell surface interactions at the vascular wall
Vesicle-mediated transport: Scavenging of heme from plasma
Gene Ontology:
Molecular function: antigen binding
Biological process: immune response
Cellular component: extracellular region; immunoglobulin complex; plasma membrane
Homologues: Orthologues: tropical clawed frog igl (56% identical). Paralogues in human: IGLV3-25 (78% identical), IGLV3-9 (77% identical), IGLV3-10 (77% identical), IGLV3-16 (75% identical), IGLV3-21 (74% identical), IGLV3-27 (73% identical), IGLV3-12 (71% identical), IGLV3-22 (70% identical), IGLV3-19 (67% identical), IGLV3-32 (63% identical), IGLV1-40 (58% identical), IGLV1-51 (58% identical), and 81 more.
Diseases named in the same sentence as IGLV3-1 in open-access papers:
IGLV3-1 is named in the same sentence as 4 diseases in open-access papers, as found by Europe PMC text mining. Sharing a sentence is not in itself a finding about the gene and the disease. The quoted sentences say what the papers report.
COVID-19 (3 papers, 2023 to 2024). A disease caused by infection with severe acute respiratory syndrome coronavirus 2. "IGLV3-1 is upregulated in the serum of patients with coronavirus disease 2019 and has been suggested as a biomarker, but the correlation between IGLV3-1 and AVN is yet to be reported." (PMID 38825675, 2024). "From these proteins CRTAC1, IGLV3-1, HRG, HSPB1, LCP1, ITIH3, and APOA2 have all been identified as correlating with COVID-19 in other research, but to our knowledge, the rest are novel." (PMID 37308820, 2023). "Specifically, signatures of plasma cells (IGHG3, IGKC, IGHM, JCHAIN, IGHG2, IGKV4-1, IGLV3-1, IGHA1), activated fibroblasts (COL1A1, COL1A2, COL3A1), inflammatory cytokines (CXCL9, CCL18) and complement factors (C1QB, C1QC) dominated the DE genes for the COVID-19 lung sections." (PMID 37858234, 2023).
tumor (2 papers, 2013 to 2023). "Of note, the up-regulated IGLV3-1 gene (in U animals) encodes an antibody of the innate immune system that has been shown to induce tumor-specific cell death via intracellular lipid accumulation, a process that is named lipoptosis." (PMID 24260100, 2013). "In addition, the lesion IgG + and mucosa IgA + spots exhibited divergent B-cell receptor V/C gene usage, with IGLC2, IGLC3, IGLV3-1, and IGKV4-1 all enriched in the tumor, suggesting a difference in the adaptive response between the two plasma cell types." (PMID 38110959, 2023).
cancer (1 paper, 2020). A tumor composed of atypical neoplastic, often pleomorphic cells that invade other tissues. "Even though sEVs B cell markers expression was invariant between control and cancer, IGLV3-1 was significantly upregulated, after correcting for multiple testing (>one order of magnitude), in sEVs BAL fraction from cancer patients compared to control." (PMID 33233545, 2020).
IGLV3-1 also shares sentences with these, for which no sentence is quoted: infection (1 paper).